FLG (filaggrin)
Diseases named in the same sentence as FLG in open-access papers (continued):
Sharing a sentence is not in itself a finding about the gene and the disease.
anaphylaxis (2 papers, 2019 to 2023). An acute hypersensitivity reaction that occurs from exposure to an allergen. "Through downregulating filaggrin (FLG) expression, IL-4 also amplifies the effects of histamine and stimulates immunoglobulin E (IgE) production by B cells, which could inhibit skin barrier function and induce pruritus or anaphylaxis in skin lesions of acute AD." (PMID 37325349, 2023). "There are two contradicting reports showing wheat-dependent exercise-induced anaphylaxis (WDEIA) in a patient without filaggrin mutation and an association of mutation in the filaggrin gene with WDIEA in a Japanese family." (PMID 30909404, 2019).
atopic march (2 papers, 2019 to 2023). sequential manifestations of different allergic diseases such as eczema, asthma and rhinitis. "In this review, we focus on the FLG molecule and its importance in maintaining normal skin barrier function and on current knowledge of the significance of FLG deficiency in diseases associated with atopic march." (PMID 31223255, 2019). "Most of the scientific articles included in this review consider FLG deficiency, in particular caused by the FLG mutation, as one of the causes, the key risk factor, the AD modifier, and consequently the possible causes of atopic march." (PMID 31223255, 2019). "The most investigated causes of the epidermal skin barrier impairment in AD, as the initiator of atopic march, are a lack of filaggrin (FLG) associated with decrease of ceramide and significant activation of epidermal proteases." (PMID 31223255, 2019).
autoimmune disease (2 papers, 2018 to 2022). A disorder resulting from loss of function or tissue destruction of an organ or multiple organs, arising from humoral or cellular immune responses of the individual to their own tissue constituents. "Notably, citrullination of cytoskeletal proteins such as vimentin, fibrin, collagen II and filaggrin has been reported in various autoimmune diseases." (PMID 36401289, 2022).
chronic idiopathic urticaria (2 papers, 2017 to 2025). Chronic form of idiopathic urticaria. "Increased filaggrin expression was found to be correlated with severity scores in chronic spontaneous urticaria (CSU); however, the role of filaggrin breakdown products (FBPs) in CSU has not been studied." (PMID 28465560, 2017).
colon adenocarcinoma (2 papers, 2015 to 2019). "Common variants overlapping TCGA mutations on the sinonasal and brain samples were found primarily on the filaggrin (FLG) gene, notably a missense mutation on FLG R1469H for lung squamous cell carcinoma, and another on FLG R1469L for colon adenocarcinoma." (PMID 31438887, 2019). "Human colon adenocarcinoma cells (Caco-2) were treated with the partially purified and freeze dried WSE from legume D and S aiming at investigating filaggrin (FLG) and involucrin (IVL) gene expressions through RT-PCR." (PMID 26494432, 2015).
colon cancer (2 papers, 2021 to 2024). "In colon cancer, FLG mutation was associated with an increased risk of death due to translocation of gut bacteria and dysregulation of the immune response." (PMID 39830210, 2024).
cyst (2 papers, 2020 to 2025). A sac-like closed membranous structure that may be empty or contain fluid or amorphous material. "Large cyst-like structures are maintained in adult Gli2/3EKO skin and are also positive for squamous marker expression, e.g. filaggrin (Fig. EV3A–F)." (PMID 40859032, 2025). "Significant amounts of filaggrin are expressed in cyst formation with retention hyperkeratosis." (PMID 32765835, 2020). "Interestingly, K10 and filaggrin, markers for supra-basal keratinocytes within the interfollicular epidermis, were both detected in the cyst-like abnormal HF structures in Gli2/3EKO mice, but not in HFs of littermate controls." (PMID 40859032, 2025).
eosinophilic esophagitis (2 papers, 2020 to 2023). Eosinophilic esophagitis (EoE) is a chronic, allergic disease of the esophagus characterized clinically by symptoms of esophageal dysfunction (including vomiting, dysphagia, feeding disorders, food impaction and abdominal pain) which persist after treatment with proton pump inhibitors (PPIs). "Due to the finding of single nucleotide polymorphisms in genes encoding eotaxin‐3, TGF-β1, filaggrin, TSLP and TSLP receptor, a genetic susceptibility to eosinophilic esophagitis is suggested." (PMID 32601726, 2020).
Erythema (2 papers, 2020 to 2021). Redness of the skin, caused by hyperemia of the capillaries in the lower layers of the skin. "In particular, the efficacy of XG associated with PP is related to the modulation of the erythema formation, mast cell infiltration, TJs, and filaggrin in the skin." (PMID 32438777, 2020).
ischemic stroke (2 papers, 2021 to 2022). A stroke disorder caused by obstruction of blood flow to the brain, due to thrombotic (local blood clot formation) or embolic (due to a blood clot or other material traveling from another site) event. "Essential filaggrin gene mutations, which were observed in AD aged 20 years or older, were related to the ischemic stroke risk (OR = 1.15, 95% CI = 1.02–1.30)." (PMID 36362231, 2022). "FLG mutations were associated with athopic dermatitis with increased ischemic stroke risk in the general population." (PMID 34976023, 2021). "Since the detailed molecular mechanisms of direct filaggrin-mediated ischemic stroke event have not been elucidated, this might simply indicate that filaggrin-mediated skin barrier dysfunction enhanced AD skin inflammation, leading to the development of vascular events." (PMID 36362231, 2022).
multiple sclerosis (2 papers, 2008 to 2021). A progressive autoimmune disorder affecting the central nervous system resulting in demyelination. "In this study, a cohort of RA sera, healthy control sera and multiple sclerosis sera were screened for reactivity to a variety of citrullinated peptides originating from α-enolase, pro-filaggrin, proteoglycan and Epstein–Barr nuclear antigen-2 by enzyme-linked immunosorbent assay." (PMID 34449533, 2021).
Obesity (2 papers, 2017 to 2022). Accumulation of substantial excess body fat. "With the complex aetiology of AD, involving both genetic factors, such as filaggrin (FLG) mutations, and environmental factors, the increased prevalence of obesity and overweight in early childhood could contribute to the AD epidemic seen in children." (PMID 28592289, 2017).
Sepsis (2 papers, 2023 to 2024). Sepsis is defined as life-threatening organ dysfunction caused by a dysregulated host response to infection. "Interestingly, the IV patients in our cohort who experienced sepsis had either frameshift or nonsense mutations in the N-terminal half of FLG whereas those having mutations toward C-terminal region of the FLG gene did not experience sepsis." (PMID 38627868, 2024).
vitiligo (2 papers, 2020 to 2022). Generalized well circumscribed patches of leukoderma that are generally distributed over symmetric body locations and is due to autoimmune destruction of melanocytes. "We suggest further studies are needed to determine the roles of TGFB3 and FLG in VKH and vitiligo." (PMID 33384688, 2020). "Profilaggrin (gene name FLG), a protein hormone that promotes hair growth, and SFRP2, a soluble regulator of WNT signaling, were significantly upregulated in VKH but not vitiligo." (PMID 33384688, 2020). "The upregulation of FLG in VKH and not in vitiligo was an unexpected finding." (PMID 33384688, 2020). "We hypothesize that increased FLG expression in VKH dogs suggests a process of chronic inflammation in hair follicles, which is lacking in vitiligo." (PMID 33384688, 2020).
allergic asthma (1 paper, 2016). A asthma with a basis in a pathological type I hypersensitivity reaction. "In this sense, it could be interesting to interrogate possible differences regarding filaggrin expression in the bronchial mucosa between allergic and non allergic asthma to assess implication of SNPs in the filaggrin gene." (PMID 27462351, 2016).
ankylosing spondylitis (1 paper, 2021). An autoimmune chronic inflammatory disorder characterized by inflammation in the vertebral joints of the spine and sacroiliac joints. "The levels of citrullinated collagen, and filaggrin were significantly higher in RA sera than in sera of healthy control, ankylosing spondylitis (AS), or systemic lupus erythematosus (SLE) patients." (PMID 34305925, 2021). "Subsequently, serum levels of citrullinated type II collagen and filaggrin were measured in healthy volunteers, patients with RA, ankylosing spondylitis (AS), and systemic lupus erythematosus (SLE) using a 12G1-based sandwich ELISA." (PMID 34305925, 2021).
Autoimmunity (1 paper, 2025). The occurrence of an immune reaction against the organism's own cells or tissues. "For instance, EBV nuclear antigen 1 (EBNA1) contains peptide motifs with homology to citrullinated peptides such as filaggrin and type II collagen, which are key targets in RA-associated autoimmunity." (PMID 40564838, 2025).
basal cell carcinoma (1 paper, 2023). A carcinoma involving the basal cells. "In particular, significant FLG mutations were found in the high ROSig group, and studies suggest that loss of FLG function due to mutations may increase the risk of basal cell carcinoma, which may also be a mechanism for the worse prognosis of patients in the high ROSig group." (PMID 37404810, 2023).
bladder urothelial carcinoma (1 paper, 2023). "Particularly, Chen and collaborators described by means of cellular experiments that filaggrin is an oncogene in bladder urothelial carcinoma (BLCA), and that a knockdown of this barrier protein suppressed BLCA cell proliferation and promoted apoptosis." (PMID 37284199, 2023).
cardiomyopathy (1 paper, 2023). A disease of the heart muscle or myocardium proper. "Exome sequencing revealed that Individual 2 harbored a heterozygous pathogenic variant in SCN5A, associated with autosomal dominant cardiac conduction system dysfunctions and cardiomyopathy, and Individual 24 had a heterozygous pathogenic variant in FLG, associated with autosomal dominant eczema." (PMID 37077567, 2023).
cholesteatoma (1 paper, 2015). A pathologic process characterized by the proliferation of keratinizing squamous epithelium resulting in the accumulation of keratin and cells in the middle ear and/or mastoid. "Previous data suggests an interaction between FLG and involucrin (IVL), a protein that creates a protective envelope around corneocytes, and increased IVL in cholesteatoma; we identified increased IVL in cholesteatoma matrix, but not at levels meeting detection threshold (1.97-fold increase)." (PMID 26608071, 2015).
cystic teratomas of the ovary (1 paper, 2022). "Among the 15 prevalent mutated genes, 8 with different variants in exons with changes in protein coding are important for the development of mature cystic teratomas of the ovary: FLG, MUC17, MUC5B, RP1L1, NBPF1, SLC29A3, SGK223, and FAM186A." (PMID 36289533, 2022).
egg allergy (1 paper, 2025). A food allergy that is an allergy or hypersensitivity to dietary substances from the yolk or whites of eggs, causing an overreaction of the immune system which may lead to severe physical symptoms. "This association was particularly pronounced in children with compromised skin barrier function, either due to filaggrin (FLG) loss-of-function mutations resulting in reduced FLG expression, in those with AD, or in those with pre-existing egg allergy." (PMID 41153664, 2025).
endometrial cancer (1 paper, 2023). Primary or metastatic malignant neoplasm involving the endometrium (mucous membrane that lines the endometrial cavity). "Cell division cycle 5-like protein (CDC5L) and Filaggrin (FLG) exhibited the largest fold changes, being sevenfold higher and lower in endometrial cancer compared to controls, respectively." (PMID 36807337, 2023).
ependymoma (1 paper, 2024). A WHO grade II, slow growing tumor of children and young adults, usually located intraventricularly. "BST1, FLG, KANK4, and SHISA9 were significantly higher expressed in SP-EPN subtype A compared to all other ependymomas, whereas AK5, CFTR, RASSF6, and TBX22 showed high expression in subtype B." (PMID 38265489, 2024).
equine disease (1 paper, 2025). "Currently, there is no published study on equine filaggrin, either in normal or in atopic skin; thus, the role of filaggrin in equine disease is completely unknown." (PMID 40005851, 2025).
folliculitis (1 paper, 2024). Inflammation of the hair follicles. "Folliculitis observed with tapinarof can be associated with increased follicular cornification with subsequent plugging, resulting from the upregulation of stratum corneum components, including filaggrin, hornerin, and involucrin." (PMID 39150292, 2024).
lymph node metastasis (1 paper, 2024).
mastocytosis (1 paper, 2017). A clonal myeloproliferative neoplasm characterized by the proliferation and accumulation of neoplastic mast cells in one or multiple organs or organ systems. "It has been proven that diseases, such as mastocytosis, defects in HLA, or filaggrin genes, increase the risk of severe allergic episodes." (PMID 28559894, 2017).
metastatic tumor (1 paper, 2016). "Unique mutations in PCLO and CSMD3 in P3A and P3B, respectively and FLG, MLL3 and SPEN in metastatic tumor M3A are listed in the branches." (PMID 27034009, 2016).
periodontitis (1 paper, 2022). An acute or chronic inflammatory process that affects the tissues that surround and support the teeth. "Moreover, the first clinical ACPA test detected antibodies in RA sera that bound citrullinated filaggrin in buccal mucosa, supporting a link between the oral mucosa/Pg/periodontitis and ACPA + RA." (PMID 35207282, 2022).
rosacea (1 paper, 2025). A chronic erythematous skin disorder that affects the face. "Analysis focused on claudin-1 due to its central role in LL-37-mediated barrier disruption; filaggrin and loricrin were not assessed but are often similarly affected in rosacea models." (PMID 41296102, 2025).
seborrheic dermatitis (1 paper, 2021). A chronic, inflammatory skin disorder that affects the scalp, central face and skin folds; it is characterized by scaling and itching. "Upregulate FLG and IVL genes in keratinocytes in vitro.Induce proinflammatory mediators in keratinocytes in vitro.Associated to exacerbated AD and seborrheic dermatitis." (PMID 34831399, 2021).
skin abnormalities (1 paper, 2021). "The most widely established cause for skin abnormalities related to FLG are the loss-of-function mutations of the FLG gene that result either in a reduction in the amount of FLG protein or complete loss of FLG and its degradation products." (PMID 34198894, 2021).
steroid sulfatase deficiency (1 paper, 2021). "Interestingly, filaggrin mutations can also be observed in X-linked recessive ichthyosis underlying steroid sulfatase deficiency." (PMID 34066992, 2021).
Stroke (1 paper, 2013). Sudden impairment of blood flow to a part of the brain due to occlusion or rupture of an artery to the brain. "Moreover, in supplemental analyses by mutation, we did observe a statistical significant association between one of the loss-of-function mutations in FLG and stroke." (PMID 24367652, 2013).
urticaria (1 paper, 2025). A vascular reaction of the skin characterized by erythema and wheal formation due to localized increase of vascular permeability. "Variations in several other genes, such as SOCS5, FLG and angiotensin‐converting enzyme, are known to increase the susceptibility of other multisystem immune‐related disorders, but their role in urticaria remains to be identified." (PMID 40635160, 2025).
vitamin D deficiency (1 paper, 2025). A nutritional condition produced by a deficiency of VITAMIN D in the diet, insufficient production of vitamin D in the skin, inadequate absorption of vitamin D from the diet, or abnormal conversion of vitamin D to its bioactive metabolites. "Vitamin D deficiency:Abnormal differentiation of corneal cells (decreased filaggrin) → permanent damage to the barrier.Vitamin B6 deficiency → tryptophan metabolism tends towards indolamine (pro-inflammatory)." (PMID 40735411, 2025).